IL33 (interleukin 33)
Diseases named in the same sentence as IL33 in open-access papers (continued):
Sharing a sentence is not in itself a finding about the gene and the disease.
helminth infection (continued). "The relevance of IL-33 in the immune response against helminth infection in humans remains unclear, possibly due to the limitations that exist in studying human ILC2s." (PMID 34759931, 2021). "Some studies have reported an increase in IL-33 during helminth infections, including T. canis." (PMID 34324507, 2021). "In the lung, IL-33 participates in the activation of most of the inflammatory processes in which ILC2s are involved; it does so by inducing the expression of IL-5 and IL-13, mainly in models of upper airway inflammation or helminth infection." (PMID 34759931, 2021). "Beginning with the damage of epithelial cells and their subsequent IL-33 release in response to helminth infection, cells of the host immune system respond in a type-2 manner which has been shown to be necessary in a number of recent human studies and animal models." (PMID 32363166, 2020). "Together these studies suggest that in some helminth infection models signaling through IL-33 may be essential for EAE disease protection." (PMID 33117327, 2020). "Studies by our group and others show that DC-derived IL-33 is sufficient to promote subsequent Th2 immunity in response to IgG immune complexes, and macrophage-derived IL-33 has shown a similar function to promote Th2 immunity during helminth infection." (PMID 31940364, 2020). "As deficiency in either IL-25 or IL-33 results in greatly enhanced susceptibility to helminth infection, these alarmins are not generally redundant." (PMID 31024526, 2019). "However, the mechanism by which IL-33 is induced and released to act upon ILC2s during helminth infection remains unresolved." (PMID 31072011, 2019). "Indeed, we demonstrated that mice whose T cells lack RORα mounted equivalent type 2 adaptive immune responses to parasitic worm infection, papain allergen, and IL-33 as RORα-sufficient T cell controls." (PMID 29907525, 2018). "However, the liver MNCs in male-only worm infection had a poor response to IL-33, though elevated serum IL-33 was observed." (PMID 27445267, 2016). "However, the liver MNCs in mice with male-only worm infection displayed a poor response to IL-33, though elevated serum IL-33 was observed." (PMID 27445267, 2016). "Apart from their temporal origin, ILC2s exhibit a tissue-dependent responsiveness to IL-33 and IL-25, with IL-33-responding ILC2s residing mainly in the lung and adipose tissue in steady-state conditions and IL-25-responding ILC2s mainly found in the intestine upon helminth infection." (PMID 36305904, 2022). "This suggests that ILC2s may acquire a lasting imprint of intestinal origin, making them more receptive to pulmonary stimuli like IL-33 than lung-derived nILC2s and offering a potential explanation for their heightened capacity to clear pulmonary helminth infections." (PMID 36044863, 2022). "IL-4 and IL-33 indeed have profound effects on the metabolism and epigenetic signature of macrophages, but whether the same pathways govern trained immunity during helminth infection requires further investigation." (PMID 36065058, 2022). "IL-33 is related to the increase in eosinophils, and although this cell is considered important for the control of helminth infections, studies suggest that in T. canis infection, eosinophils may have a limited ability to kill these helminths and the larvae can escape efficiently from these cells." (PMID 34324507, 2021). "The cytokines IL-25 and IL-33 (a member of the IL-1 family) have been shown to play a crucial role in the regulation of type 2 cytokine production, to be produced rapidly following helminth infection, and to promote protective immunity against Trichuris muris, Nippostrongylus brasilienis and Hp." (PMID 23935505, 2013). "Although already present at high levels in the steady state, the expression of IL-33 can be further increased during inflammation, such as in COPD, graft-versus-host disease, helminth infection, and AD." (PMID 39962262, 2025).
helminth infection (continued). "Damaged IECs release cytokines such as IL-33, IL-25, and thymic stromal lymphopoietin (TSLP), playing a crucial role in worm infections." (PMID 38203591, 2023). "After worm infection, GSDMC promoted the secretion of the “alarmin” cytokine interleukin-33 (IL-33) by intestinal epithelial cells to initiate type 2 responses for worm clearance and tolerance." (PMID 38022612, 2023). "IL-33 and TSLP activate IL-9 production by ILC2s which further induces IL-5 and IL-13 during helminth infection." (PMID 36969171, 2023). "During helminth infection, IL-33 is a potent cytokine for expanding ILC2/M2/Tregs and inducing IL-13 production, suggesting that IL-33 is critical to eliciting type 2 immune responses." (PMID 36271450, 2022). "These include IL-33, IL-25 and TSLP, a prototypical group of cytokines produced in response to specific stimuli such as tissue damage by allergen exposure, and helminth infection, which induce type 2 immune responses." (PMID 34759931, 2021). "Ultimately, mice with ineffective mast cells are unable to prime an effective type 2 immune response regulated by IL-33, IL-25 and TSLP in response to helminth infection and are unable to clear the parasites." (PMID 32363166, 2020). "EGFR expression on Th2 cells is critical for resistance during GI helminth infection and a signalling complex between EGFR and ST2 can activate Th2 cells to secrete IL-13 in an antigen-dependent manner upon IL-33 exposure." (PMID 32636457, 2020). "Identifying critical source(s) of IL-33 and uncoupling the intra- and extra-cellular functions of IL-33 will be important for understanding how IL-33 regulates ILC2 activation and function during helminth infection." (PMID 31072011, 2019). "In the context of helminth infection with N. brasiliensis, lung ILC2s express OX40L in response to IL-33 stimulation allowing enhanced communication with OX40+ T-cells." (PMID 31024526, 2019). "This correlation between reductions in these epithelial derived cytokines and the delayed Th2 response seen experimentally is further evidence in support of the Th2 polarizing effect of IL-25, IL-33 and TSLP in certain helminthic infections." (PMID 30670631, 2019). "Recent studies have found that ATII cells are the major source of IL-33 at baseline and upon lung inflammation following exposure to OVA, ragweed, papain as well as upon certain fungal and helminth infections." (PMID 24551140, 2014). "Mast cells are required for the production of IL-25, IL-33, and TSLP by intestinal epithelial cells following helminth infection and during subsequent anti-helminth responses." (PMID 23653627, 2013). "2‐DG has no impact on IL‐33‐ or helminth infection‐induced ILC2 activation, but it reduces ILC2 responses when ILC2s are over‐activated such as in PD‐1‐deficient mice." (PMID 36181709, 2023). "Strikingly, cell-intrinsic deletion of IL-33 in myeloid APC basally alters chromatin accessibility at inflammatory cytokine loci and promotes IL-17/23-dependent epidermal thickening, keratinocyte hyperplasia, and resistance to helminth infection." (PMID 38076920, 2023). "Inhibition of mast cell function in vivo has also been linked to an overall reduction in IL-33, as well as IL-25 and TSLP both in the context of helminth infection as well as without." (PMID 32363166, 2020). "In the absence of either IL-25 or IL-33, resistance to helminth infections is severely impaired, as is the case in IL-4Rα or STAT6 deficiency." (PMID 28302598, 2017). "It has been shown that BM ILC2P and ILC2 are mobilized by IL-33 under lung allergy conditions, which, together with the expansion of preexisting tissue ILC2, is in line with the sharp increase of ILC2 in peripheral tissues during helminth infection or allergic inflammation." (PMID 36417511, 2022).
helminth infection (continued). "Overall, these results are of particular significance as they suggest that IL-25 and IL-33 may play nonredundant roles in helminth infection and discrete pathways may be needed for host immune responses to different intestinal helminth parasite infections." (PMID 28898280, 2017). "Indeed, studies in mice show that ILC2 activation in response to helminth infection or A. alternata exposure is only completely abolished in combined absence of IL-25 and IL-33 signaling." (PMID 26965110, 2016). "Also, alveolar macrophages can express IL-33 in response to influenza A infection as well as to some but not other helminth infections." (PMID 24551140, 2014). "In addition to IL-33, IL-25, which triggers the expansion and migration of inflammatory ILC2 in the small intestine during helminth infection, may represent a potential entrainer of ILC2 with enhanced type 2 cytokine production and anti-helminth effector functions." (PMID 36065058, 2022). "During helminth infection, non-hematopoietic epithelial cell-derived IL-33, triggers ILC2 activation, while myeloid-derived IL-33 is critical for the regulation of adaptive T cells." (PMID 41484668, 2026). "In general, helminth infections develop a Th2-type immune response with an increase in IL-4, IL-5, IL-13 and IL-33 cytokines, which may assist in the expulsion of worms in the lungs, but there are still no studies on the importance of the cytokine IL-33 in T. canis infection." (PMID 34324507, 2021).
liver fibrosis (75 papers, 2012 to 2026). "In the current study, we evaluated the role of the IL-33/ST2 activation pathway in the development of liver fibrosis caused by the experimental S. mansoni infection." (PMID 37373379, 2023). "Further studies have identified IL-33 as key mediator of hepatic fibrosis by demonstrating that IL-33 deficiency ameliorates liver fibrosis induced by bile duct ligation and carbon tetrachloride (CCl4)." (PMID 33841164, 2021). "ILC2s are known to expand in response to IL-33 in liver fibrosis and are a major source of IL-13, which causes hepatic stellate cell activation independently of adaptive immunity (fibrosis is not attenuated in Rag deficient mice)." (PMID 32079296, 2020). "When further reviewing chronic liver diseases, we found that IL-33 has been strongly associated with liver fibrosis in mouse models." (PMID 32486265, 2020). "The IL-33/IL-13 pathway is associated with the immunopathological process of liver fibrosis, and hepatic group 2 innate lymphoid cells (ILC2s) have been identified as fibrogenic immune cells in the murine liver." (PMID 31888743, 2019). "This study therefore aimed at investigating the association between plasma levels of IL-33, infection status and liver fibrosis profiles in school children with S. mansoni infection alone or associated with malaria, hepatitis B or hepatitis C." (PMID 31849991, 2019). "IL-33 has been further suggested as pro-fibrotic factor that is associated with liver fibrosis in chronic liver disease in mice and humans." (PMID 30213101, 2018). "For example, an excess of IL-33 causes liver fibrosis in mice via activation and expansion of group 2 innate lymphoid cells to produce type 2 cytokines, resulting in cell conversion into pro-fibrotic M2 macrophages." (PMID 26549942, 2015). "Other studies suggest that IL-33 participates in the pathogenic process of acute hepatitis induced by Con-A, and IL-33 overexpression is associated with the development of HBV/HCV-related liver fibrosis." (PMID 22315510, 2012). "Therefore, miR-203-3p can inhibit the process of schistosomiasis-associated liver fibrosis by inhibiting IL-33 secretion." (PMID 31888743, 2019). "It was possible that high levels of serum ST2 were an early marker for liver injury, while high levels of serum IL-33 may be associated with the development and progression of liver fibrosis and damage." (PMID 27180842, 2016). "It is possible that high levels of serum sST2 are an early biomarker of liver injury, while high levels of serum IL-33 may be associated with the development and progression of liver fibrosis and damage." (PMID 22315510, 2012). "All these data together suggest that the activation of IL-33 could be associated with a poor prognosis in liver fibrosis by the upregulation of type 2 immune response, leading to the increase in type 2 cytokines which are mainly the cause of biliary injuries and fibrosis." (PMID 36271450, 2022). "Phagocytosis assays, migration assays, and western blot analysis were performed to investigate the effects of IL-33 and ST-2 on eosinophils and hepatic stellate cells, so as to evaluate their roles in hepatic fibrosis and eosinophil activity." (PMID 41933369, 2026). "Numerous studies have confirmed that the Interleukin-33/T helper 2 cells (IL-33/Th2) axis contributes to liver fibrosis." (PMID 39995661, 2025). "The IL-33/ST2 signaling axis is pivotal in liver fibrosis, balancing inflammation with tissue regeneration, wound healing, and tissue repair." (PMID 39995661, 2025). "Of note, ST2 is expressed in HSCs, and the activation of IL-33 signaling in HSCs directly promotes hepatic fibrosis." (PMID 40794228, 2025). "IL-33, as a damage-associated molecular pattern (DAMP), enhances PSMP production, highlighting its critical role in hepatic fibrosis progression." (PMID 39995661, 2025). "In mouse models, IL-33 exacerbates overall liver fibrosis pathology in TAA or CCl4-induced hepatitis, suggesting that Th2 cells promote fibrosis." (PMID 40616144, 2025).
liver fibrosis (continued). "In BDL-induced hepatic fibrosis models, injury-induced release of endogenous IL-33 triggers inflammation and fibrosis." (PMID 39995661, 2025). "The role of IL-33 signaling in liver fibrosis indicates the potential profibrotic role of tissue Treg." (PMID 40616144, 2025). "The role of IL-33 in liver fibrosis warrants further exploration and holds potential as a therapeutic target for fibrosis treatment." (PMID 39995661, 2025). "sST2, which is measurable in serum, correlates well with the hepatic IL-33/ST2 activation in liver fibrosis." (PMID 38291388, 2024). "IL-33 plays an important role in the immune response to schistosome infection, and the level of IL-33 is positively correlated with the progression of egg granulomas and liver fibrosis." (PMID 38105713, 2024). "IL-33 promotes the recruitment of the second group of congenital lymphocytes (ILC2s) in the liver, and ILC2s secrete IL-13 to promote the development of liver fibrosis." (PMID 38105713, 2024). "Recently, it has been demonstrated that IL-33 play key roles in type 2 cytokine-driven inflammation and fibrosis; moreover, promote ischemia-reperfusion induced renal or hepatic fibrosis in mice." (PMID 38726105, 2024). "IL-33 induces M2-type polarization in macrophages and the release of IL-5 and IL-13 to promote liver fibrosis." (PMID 38105713, 2024). "IL-33 stimulates Th2 cells to produce cytokines, inducing liver fibrosis while reducing liver damage in a murine model of NASH." (PMID 39359475, 2024). "As demonstrated in other models of liver fibrosis, IL-13 can be activated via the IL-33 pathway, implying that the liver fibrosis mechanisms during schistosomiasis are mainly driven by a balance between IL-33 and IL-13 instead of TGF-β." (PMID 37373379, 2023). "The opposite effects of IL-33 resembled those observed in liver fibrosis, where it is tissue-protective when acute, whilst it functions as a pro-fibrotic hepatic factor in cases of chronic injury." (PMID 36768322, 2023). "Some authors have already reported this linkage of IL-33 with macrophages and the development of pulmonary, renal, and liver fibrosis due to S. japonicum infection." (PMID 37373379, 2023). "Liver fibrosis induced by thioacetamide and CCl4 administration or Helicobacter hepaticus infection also showed the essential role of the IL-33/ST2 signalling pathway in the pathological alterations." (PMID 37373379, 2023). "During hepatic fibrosis, IL-33 and ST2 mRNA and protein levels were increased in murine and human fibrotic livers compared to healthy controls." (PMID 38566909, 2022). "During chronic infections, Hepatic progenitor cells (HPCs) inhibit the secretion of IL-33 to promote tissue restoration and inhibit the development of liver fibrosis." (PMID 36389166, 2022). "IL-33 promotes the recruitment of Group 2 innate lymphoid cells (ILC2s) in the liver, and secretion of IL-13 by ILC2s promotes the development of liver fibrosis." (PMID 36389166, 2022). "IL-33 plays an important role in immunity to schistosome infection, and IL-33 levels are positively correlated with the progression of egg granuloma and liver fibrosis." (PMID 36389166, 2022). "In order to understand the association between IL-33 and liver fibrosis, the level of TGF-β1 was measured and correlated to the IL-33 level." (PMID 35056005, 2022). "IL-33 induces macrophage M2-type polarization and releases IL-5 and IL-13 to promote liver fibrosis." (PMID 36389166, 2022). "Current data show that, in contrast to IL-17, serum levels of IL-33 significantly increased in patients with liver fibrosis." (PMID 35056005, 2022). "In liver disease, as observed during liver fibrosis and hepatitis B, stressed hepatocytes release IL-33, which was demonstrated to protect hepatocytes by simultaneously repressing the expression of proapoptotic genes and activating antiapoptotic genes." (PMID 36088327, 2022).